AR (androgen receptor)
Diseases named in the same sentence as AR in open-access papers (continued):
Sharing a sentence is not in itself a finding about the gene and the disease.
Insulin resistance (66 papers, 2010 to 2026). Increased resistance towards insulin, that is, diminished effectiveness of insulin in reducing blood glucose levels. "The increased sensitivity of the androgen receptor has been linked to the development of insulin resistance in postmenopausal women." (PMID 39204191, 2024). "Long‐term androgen receptor activation in females has been shown to predispose to insulin resistance, combined with up‐regulation of genes involved in HDL catabolism leading to dyslipidaemia." (PMID 37736873, 2023). "In particular, the pattern of AR expression in the liver is associated with disorders such as visceral obesity, leptin, and insulin resistance, and lipid metabolism disorders." (PMID 36359245, 2022). "For example, it is known that the activation of the androgen receptor decreases lipogenesis in type 2 diabetes, which is associated with lower insulin resistance." (PMID 31925559, 2020). "We learned the impact of testosterone deficiency on the development of visceral obesity and insulin resistance in men, and a recent study revealed a potential mechanism, involving extranuclear actions of the androgen receptor in regulating insulin secretion." (PMID 31589598, 2019). "Low expression of AR is linked with elevated insulin resistance on a high-fat diet with decreased β-oxidation of fatty acids." (PMID 30678306, 2019). "Previous studies utilising liver-selective AR KO mice have implicated AR as a positive factor in preventing the development of hepatic steatosis and insulin resistance." (PMID 23451233, 2013). "Additionally, the accumulation of VAT can also lead to an increase in aromatase levels, causing insulin resistance and a reduction in myogenesis via androgen receptor-mediated pathways." (PMID 38887271, 2024). "While a reduction in testosterone, DHT, and/or AR signaling has been associated with abdominal obesity, hyperglycemia, insulin resistance, leptin resistance, metabolic syndrome, and type 2 diabetes in males, it has been related to an improved metabolic phenotype in females." (PMID 37404855, 2023). "Furthermore, a hepatic androgen receptor deficiency decreases fatty acid oxidation and increases hepatic de novo lipogenesis by decreasing PPARα expression, which causes hepatic steatosis and insulin resistance." (PMID 38075062, 2023). "The adrenal hormones may, on the one hand, activate at least mutated AR, a frequent mechanism in PCa to provoke resistance to hormonal therapy, but on the other hand, also elevate fasting glucose levels in PCa patients by introducing insulin resistance." (PMID 36431238, 2022). "Interestingly, hepatic AR-knockout mice similarly develop insulin resistance, indicating that loss of AR function in SBMA patients may contribute to this phenotype." (PMID 31686397, 2019). "We believe that the relationship between testosterone and diabetes can be mainly explained from three aspects: insulin resistance, inflammation and oxidative stress, and androgen receptor (AR)." (PMID 41180176, 2025). "Note that individuals assigned male sex at birth who were treated with estrogens (and androgen depletion) as gender-affirming therapy developed insulin resistance, suggesting that in males, E2 improves insulin sensitivity in the presence of intact AR action." (PMID 39225098, 2024). "Specific fat tissue AR knockdown (fARKO) mice developed metabolic dysregulation on a normal diet with early insulin resistance and hyperinsulinemia." (PMID 39123669, 2024). "We therefore clarify how testosterone induces insulin resistance in female adipocytes and impairs insulin-mediated glucose uptake through the activation of selective metabolic signaling pathways and androgen receptor alterations." (PMID 37374053, 2023). "We detected increased expression of Insulin-like receptor (InR) and Thor encoding Drosophila homologue of the initiation factor 4E-binding protein (4E-BP), which are indicators of insulin resistance, in AR mutants." (PMID 35687590, 2022).
Insulin resistance (continued). "This study presented a new potential relationship between miRNAs and the AR that is worth considering in further investigations into insulin resistance." (PMID 35163477, 2022). "Many studies indicate that AR deletion contributes to the development of late visceral obesity with leptin resistance, insulin resistance and increased lipogenesis in adipose tissue and the liver." (PMID 33513940, 2021). "This study addresses the effects of the androgen receptor and its blockade on plasma insulin and glucose as well as an index of insulin resistance." (PMID 33393733, 2021). "Animal studies showed that targeted deletion of the androgen receptor in male mice leads to increased blood glucose levels from insulin resistance." (PMID 33537005, 2020). "Administration of flutamide reverses DHT-induced hepatocyte insulin resistance, supporting an AR-driven mechanism." (PMID 32310267, 2020). "Insulin resistance is another important biological process related to visceral fatness and endocrine signaling, where 41 AR-DE genes were expressed higher in the LG chickens and 30 genes were more abundant in the HG." (PMID 28814270, 2017). "The total AR knockout mice develop liver steatosis and insulin resistance in both male and female mice." (PMID 26491440, 2015). "AR can be an important link between inflammation and insulin resistance, while MEF2A has role in insulin signaling." (PMID 24303025, 2013). "Testosterone replacement resulted in improved glycemic control in hypogonadal men with type 2 diabetes and androgen receptor knockout male mice manifested insulin resistance and impaired glucose tolerance." (PMID 23066943, 2012). "Up-regulated in states of insulin resistance, IL-6 differentially regulates androgen receptor transactivation via three distinct signaling transduction pathways, the overall effect depending on the balance among these pathways and the androgen concentrations." (PMID 22713099, 2012). "This was confirmed by qPCR, suggesting that differences in AR levels in I-Sen and I-Res male individuals could potentially contribute to some of the insulin resistance changes in male individuals, as well as the sex-specific changes." (PMID 38032738, 2024). "In female mice, androgen excess seems to promote chronic androgen receptor activation in pancreatic beta cells, leading initially to increased basal insulin secretion independently of insulin resistance and, eventually, to beta cell failure and hyperglycaemia through oxidative stress." (PMID 36484476, 2023). "Rodent models also suggest that, independent of insulin resistance, androgen excess causes chronic androgen receptor activation in beta cells, promoting insulin hypersecretion, and secondary beta cell failure." (PMID 36484476, 2023). "Also, both global and liver-targeted AR-deleted male mice showed abnormal hepatic steatosis and insulin resistance." (PMID 36572925, 2022). "Besides, AR signaling also plays a vital role in mediating the effect of androgen in liver lipid metabolism, as hepatic AR-knockout mice was characterized by hepatic steatosis and insulin resistance." (PMID 35237237, 2022). "Moreover, ablation of neuronal AR resulted in hypothalamic insulin resistance, which leads to systemic insulin resistance, dysregulation of glucose homeostasis and lipid metabolism and visceral obesity." (PMID 33514065, 2021). "In fact, only LARKO males but not females show impaired DNL and FAO and develop hepatic steatosis and insulin resistance, suggesting that hepatic AR may play a more critical role in liver lipid metabolism of males than females." (PMID 34572151, 2021). "So, the hepatic androgen receptor (as a positive factor), could also play an important role in avoiding insulin resistance development." (PMID 33513940, 2021). "Thus, considering the potential involvement of T in regulating insulin sensitivity, a compensatory increase in the expression of androgen receptor in a setting of insulin resistance in HH and T2DM is expected." (PMID 33537005, 2020).
Insulin resistance (continued). "In male rodents, androgens, by regulating genes involved in hepatic lipogenesis and glucose metabolism, protect from NAFLD and insulin resistance through a dual mechanism: via androgen receptor signaling and via estrogen receptor signaling (following aromatization of testosterone to estradiol)." (PMID 31212642, 2019). "Men with genetic androgen resistance due to decreased AR expression develop visceral obesity, and AR knockout mice demonstrate higher visceral adiposity and insulin resistance, suggesting that androgens may suppress WAT mass both in humans and rodents." (PMID 25646091, 2014). "Hepatic AR-knockout mice fed a high-fat diet develop hepatic steatosis and insulin resistance, suggesting that decreased hepatic androgen availability in 5αR1−/− mice may contribute to increased steatosis." (PMID 24080367, 2013). "Furthermore, neuronal AR KO mice develop insulin resistance and increased fat mass in mice." (PMID 40023399, 2025). "Or, it could be possible that corticosterone‐driven insulin resistance could increase plasma glucose which would then stimulate the release in insulin, and that this could be modulated by AR blockade." (PMID 33393733, 2021). "Whereas these two previous studies linked PCOS to SNPs in genes related to glucose metabolism and insulin resistance, we focused on FKBP5, which is known to function as an androgen receptor." (PMID 35787810, 2022). "AR knockout (ARKO) male mice developed late-onset obesity, and liver-specific ARKO male mice were characterized by increased insulin resistance and steatosis, with decreased β-oxidation, upon being fed a high-fat diet (HFD)." (PMID 36359245, 2022). "Further investigations are required to elucidate the mechanisms driving insulin resistance in PCOS, including the role of AR actions in skeletal muscle, liver, and adipocytes, as well as the interplay of diet." (PMID 32310267, 2020). "Under the “Insulin Resistance” category, IPA identified 12 AR-DEGs that were more abundant in E18 embryo liver, while 16 genes were more abundant in E20 than in E18 embryos." (PMID 30241500, 2018). "Liver-specific AR KO female mice were prevented from DHT-induced insulin resistance but did not affect healthy levels of circulating androgens." (PMID 40023399, 2025). "Male mice lacking AR in β cells (βARKO mice) developed β cell failure, leading to inadequate compensation for insulin resistance and hyperglycemia." (PMID 39225098, 2024). "Male but not female mice lacking AR in the liver develop hepatosteatosis and insulin resistance upon HFD." (PMID 34576136, 2021). "Male, but not female, androgen receptor (AR) knockout mice fed a high-fat diet develop hepatic steatosis and insulin resistance with an increased expression of lipogenic genes and a decreased expression of fatty acid oxidation genes." (PMID 27757845, 2017). "Additionally, the effects of androgen on glucose metabolism may be age-specific, as one strain of androgen receptor knockout (ARKO) mice with C57BL/6 and 129 Sv backgrounds develop accelerated hyperglycemia and insulin resistance with age45." (PMID 34873153, 2021). "In addition, differently from total AR knockout mice, which develop liver steatosis and insulin resistance in both sexes, the lack of AR in the liver accounts for sex-specific metabolic consequences." (PMID 34572151, 2021). "However, treatment with androgen receptor antagonists does not always improve insulin resistance; thus, androgens may not entirely be responsible for insulin resistance but rather a contributing factor." (PMID 39458485, 2024). "However, how AR might play a role in lipid-induced insulin resistance is not fully understood." (PMID 38425436, 2024).
hypospadias (56 papers, 2007 to 2026). Hypospadias is the displacement of the urethral meatus on the ventrum of the penis. "Some EDCs also have estrogenic activity, which further derails androgen signaling by reducing AR expression or interfering with testosterone production, thus causing or increasing the risk of hypospadias." (PMID 41596366, 2026). "Although the link between AR function and hypospadias is well established, genome-wide association studies (GWAS) have identified AR variants in less than 10% of cases." (PMID 41596366, 2026). "Although mRNA studies appeared more symmetric, they still had low power due to the sample size and low strength of association between AR expression and hypospadias." (PMID 41596366, 2026). "In rodent models, developmental exposure to a wide range of EDCs consistently causes hypospadias and dysregulated AR expression, though direction and magnitude vary across studies." (PMID 41596366, 2026). "This critical role of AR signaling in penis differentiation explains why developmental exposure to various anti-androgenic chemicals can cause hypospadias in rodent offspring, as seen with different AR antagonists." (PMID 41019341, 2025). "A large-scale whole-exome sequencing (WES) study revealed that approximately 27% of severe hypospadias cases carried rare damaging variants in genes critical to testosterone synthesis and signaling, including AR, NR5A1, and SRD5A2." (PMID 41595460, 2025). "Other potential signaling pathways involved are the Fibroblast Growth Factor (Fgf) and Wnt-signaling pathways, which are both transcriptionally affected by antagonism of AR in mice, and knockout of Fgf receptor 2 causes severe hypospadias in mice." (PMID 41019341, 2025). "AR deficiency disrupts androgen signaling, impairing male sex differentiation and potentially contributing to hypospadias pathogenesis." (PMID 40948500, 2025). "To resolve this controversy, we employed a large cohort to definitively establish the AR-hypospadias association." (PMID 40948500, 2025). "This convergence of protein and gene evidence reinforces AR deficiency as a hallmark of hypospadias." (PMID 40948500, 2025). "Our results indicate that SRD5A2 and AR genes are two top candidate genes associated with 46, XY hypospadias in Chinese patients." (PMID 34276780, 2021). "In this study, 7.4% (6/81) hypospadias was caused by AR mutation, which accounted for 33.3% (6/18) genetic abnormality of hypospadias." (PMID 34276780, 2021). "To date, over 1,000 mutations have been reported in the AR gene, and it is usually included as one of the top genes in the screening panel test for patients with hypospadias." (PMID 34276780, 2021). "Heredity and gene mutations are common causes of hypospadias, and mutations of androgen receptor, Wilms tumor protein-1, steroid-α reductase, and other genes are closely related to the occurrence of hypospadias." (PMID 34589449, 2021). "In vitro functional assay was further utilized and revealed that this mutation led to impaired AR transcriptional activity (20∼46%), decreased sensitivity for androgen ligand, and was responsible to hypospadias observed in the patient." (PMID 34276780, 2021). "The genetic data further showed that the compound damaging variants of AR genes and other risk genes existed in severe hypospadias with the variable phenotypes." (PMID 32515122, 2020). "AR mutations were observed in 3.3% of the isolated hypospadias cohort, and play an important role in the cause of hypospadias." (PMID 31856834, 2019). "Rarely micropenis is associated with 5 alpha reductase enzyme deficiency or mild defects in the androgen receptor, though patients with 5 alpha reductase enzyme deficiency are more likely to have associated hypospadias than only isolated micropenis." (PMID 28149308, 2017). "Most cases of hypospadias require one or two surgical procedures; however, the current study clearly shows that the young men with an AR mutation were more likely to have multiple procedures." (PMID 27403927, 2016).
hypospadias (continued). "Mutation analysis of the androgen receptor (AR) gene was performed in 29 patients who were suspected of having a disorder of androgen action and in 20 patients with severe hypospadias with a normal response to hCG." (PMID 22253624, 2012). "In the present study, we decided to investigate possible association of the CAG repeat length in the AR gene with the disease of hypospadias in a significantly larger patient material." (PMID 23167717, 2012). "Polymorphic variants in genes involved in the masculinisation of male genitalia, such as the androgen receptor, have been associated with some cases of hypospadias." (PMID 17343741, 2007). "Lower AR expression causes abnormal combination and dysfunction of androgens; thus, urethral development is affected, and urethral closure cannot be achieved, contributing to various hypospadias." (PMID 40948500, 2025). "Furthermore, the AR gene was also studied, particularly in patients with bilateral cryptorchidism and associated hypospadias." (PMID 41595460, 2025). "Our data support DHT trials in AR-deficient hypospadias, reinforcing this therapeutic approach." (PMID 40948500, 2025). "Furthermore, rare AR variants were significantly enriched among patients with severe hypospadias in the WES cohort." (PMID 41595460, 2025). "In both sporadic and familial hypospadias, AR gene mutations have been discovered." (PMID 34276780, 2021). "The AR p.Arg841His variant is located in the ligand‐binding domain and has been previously reported in Asian patients with androgen intensitivity syndrome (Wang, Gong, Wang, & Qin, 2017), which is known to be associated with hypospadias." (PMID 32515122, 2020). "The diverse compound rare damaging variants of AR and other hypospadias risk mutants in hypospadias might be the major reason to cause the high interpatient variability." (PMID 32515122, 2020). "Missense mutations of AR accounted for 3% of patients, which may play a critical role in the cause of isolated hypospadias." (PMID 32515122, 2020). "Although AR defect may play a causative role during the development of hypospadias, the AR expression in hypospadias is still debatable." (PMID 32515122, 2020). "Besides, another study has investigated the possible association of the CAG repeat length in the AR gene with the hypospadias; and suggested that expanded CAG repeat length has a role in modifying the risk and development of hypospadias." (PMID 24799883, 2014). "Therefore, in the present study, exon1was screened for five single nucleotide polymorphisms (SNP), and in addition, AR gene promoter region was scanned for new variations in hypospadias disease in Iranian population." (PMID 24799883, 2014). "Mutations in the AR gene that severely impact the function of the receptor can cause the syndrome of partial or complete androgen insensitivity, and have also been observed in a few cases of isolated hypospadias." (PMID 23167717, 2012). "Genes linked to these male phenotypes included the androgen receptor listed for hypospadias." (PMID 21846611, 2011). "Rats exposed to a mixture of AR antagonists, vinclozolin, procymidone, and flutamide, all acting through the same mode of action, at doses that would not have caused hypospadias alone, resulted in > 50% of the animals having hypospadias." (PMID 19057713, 2008). "Therefore, miR-6756-5p may play a pivotal role as a post-transcriptional regulator of AR in genital mesodermal cells, which could potentially contribute to hypospadias driven by AR loss in humans." (PMID 39624466, 2025). "Crucially, in vitro exposure to dihydrotestosterone (DHT) or testosterone reversed these changes in a dose-dependent manner, suggesting that epigenetic silencing of AR may underlie hypospadias by suppressing androgen responsiveness during urethral differentiation." (PMID 41595460, 2025).